AQP5 (aquaporin 5)
Diseases named in the same sentence as AQP5 in open-access papers (continued):
Sharing a sentence is not in itself a finding about the gene and the disease.
Hyperglycemia (2 papers, 2021). An increased concentration of glucose in the blood. "In conclusion, an increase in ROS, a glycation product in the submandibular gland; a decrease in AQP5, which plays an important role in salvation caused by hyperglycemia, an apoptotic signal increase; and a salivation decrease in type 2 diabetic mice were confirmed." (PMID 35056946, 2021). "Accordingly, we used immunohistochemistry staining of AQP5 to further confirm that hyperglycemia induced SGs’ dysfunction." (PMID 34987398, 2021).
hypohidrosis (2 papers, 2016 to 2022). diminished sweating in response to appropriate stimuli. "This is consistent with a work by Ma and coworkers who used a mouse model and reported that topiramate reduced sweat secretion along with a diminished AQP5 expression by sweat glands, suggesting that AQP5 may be involved in topiramate-induced hypohidrosis." (PMID 35409378, 2022).
invasive carcinoma (2 papers, 2011 to 2023). A carcinoma that is not confined to the epithelium, and has spread to the surrounding stroma. "Further studies are required to elucidate the specific underlying molecular mechanisms for 1) increased AQP5 expression with loss of subcellular polarity of expression in the invasive carcinoma; and 2) the direct association between up-regulated AQP5 expression and progression of cancer cells." (PMID 22145049, 2011).
leptospirosis (2 papers, 2013 to 2016). A contagious bacterial infection caused by spirochetes of the genus Leptospira. "Similar to our findings, a previous report on patients with leptospirosis showed an increased number of aquaporin 5 positive cells within the alveolar tissue, consistent with the hypothesis that osmotically driven water may play a role as a compensatory effect when salt transport is impaired." (PMID 27835672, 2016).
liver cancer (2 papers, 2025). An epithelial or non-epithelial malignant neoplasm that arises from the liver. "miR‐1271‐5p is downregulated in HBV‐related liver cancer cells and tissues, causing AQP5 upregulation as direct target of the miRNA." (PMID 39185567, 2025).
minimal change disease (2 papers, 2013 to 2022). "Accordingly, we investigated AQP5 and AQP2 expression by IF in kidney biopsies from 17 patients with DN and 15 with minimal change disease (MCD)." (PMID 23326416, 2013).
nasal polyp (2 papers, 2020 to 2023). "In contrast, another study reported that osmotic water permeability was increased by hyperosmotic stress in human airway epithelium cultured from human nasal polyp tissue, in association with an increase in cellular levels of AQP5 and localization of AQP5 to the apical cell membrane." (PMID 32824013, 2020). "Alan found a significant decrease in AQP5 protein expression in CRS patients with nasal polyps compared to normal patients." (PMID 36868995, 2023). "Thus, the authors suggested that the mucosal epithelial barrier is compromised in the context of CRS disease, especially CRSwNP, and that loss of AQP5, which might act as a tight junction protein, plays a role in the development of mucosal edema and the pathophysiology of nasal polyp formation." (PMID 32824013, 2020).
pancreatitis (2 papers, 2014 to 2018). Inflammation of the pancreas. "The loss of AQP1 itself does not damage the pancreas and does not cause pancreatitis in mice, which assuming the compensating effect of AQP5; however, induces a more severe disease progression." (PMID 30050452, 2018).
pneumonia (2 papers, 2018 to 2022). An acute, acute and chronic, or chronic inflammation focally or diffusely affecting the lung parenchyma, caused by an infection in one or both of the lungs (by bacteria, viruses, fungi, or mycoplasma.). "Accordingly, we tested the hypothesis that the AQP5 promoter -1364A/C polymorphism is associated with AKI in patients suffering from pneumonia evoked ARDS." (PMID 30517197, 2018). "Baseline characteristics upon ICU admission of patients with pneumonia evoked ARDS stratified for AQP5 -1364A/C genotypes (n = 136)." (PMID 30517197, 2018). "We found a significant association between the AQP5 -1364A/C promoter SNP genotype and recovery from AKI during treatment of patients suffering from pneumonia evoked ARDS." (PMID 30517197, 2018). "In pneumonia evoked ARDS, the AA genotype of the AQP5 promoter polymorphism is associated with a decreased recovery rate from AKI and this is independent of fluid balance." (PMID 30517197, 2018).
rectal cancer (2 papers, 2019 to 2020). A primary or metastatic malignant neoplasm that affects the rectum. "However, neither AQP3 nor AQP5 were correlated with ADCaqp value, which may indicate that AQP1 is mainly responsible for water transport through membranes in rectal cancer." (PMID 32576929, 2020).
skin aging (2 papers, 2020 to 2022). The gradual irreversible changes in structure of skin that occur as a result of the passage of time.. "Previous studies have reported that skin aging is accompanied by reduced AQP5 expression and that the presence of AQP5 can promote the proliferation and differentiation of skin cells." (PMID 35619903, 2022). "In conclusion, AQP5 promoted the proliferation of HaCaT cells while inhibiting their differentiation, indicating that AQP5 can maintain the potential of ESCs in skin aging." (PMID 32965322, 2020). "Based on these results, AQP5 could be a potential target for cosmetics and to prevent skin aging." (PMID 32965322, 2020).
small cell lung carcinoma (2 papers, 2010 to 2022). Small cell lung cancer (SCLC) is a highly aggressive malignant neoplasm, accounting for 10-15% of lung cancer cases, characterized byrapid growth, and early metastasis. "In small-cell lung cancer, silencing AQP5 can inhibit the invasion and migration of tumor cells, which also inhibits angiogenesis and cell proliferation signaling pathways." (PMID 35619903, 2022).
tongue squamous cell carcinoma (2 papers, 2020 to 2023). A squamous cell carcinoma that arises from the tongue. "However, AQP5 overexpression was observed in tongue squamous cell carcinoma, suggesting that AQP5 has different functions in these tumors." (PMID 32075009, 2020). "Eight genes were shown to be related to the prognosis in patients with tongue squamous cell carcinoma (AXL, SCG5, VOPP1, DCBLD2, DRAM, DUSP1, AQP5, BLNK)." (PMID 37925175, 2023).
acute respiratory failure (1 paper, 2016). Life-threatening respiratory failure that develops rapidly. "In conclusion, we showed that water and ion channels are altered in patients with acute respiratory failure due to DAD, with an increase in AQP3, AQP5 and Na-K-ATPase expression and a decrease in ENaC expression." (PMID 27835672, 2016). "In the present study, we found that the expression of water and ion channel proteins in the alveolar septum are altered in patients with acute respiratory failure due to DAD, with an increase in AQP3, AQP5 and Na-K-ATPase and a decrease in ENaC compared to control subjects." (PMID 27835672, 2016).
adenoma (1 paper, 2020). A neoplasm arising from the epithelium. "AQP5 is expressed in early adenoma, late adenoma and adenocarcinoma but is barely expressed around normal colonic mucosa." (PMID 32662230, 2020).
atherosclerosis (1 paper, 2021). A disease characterized by the build-up of fatty material and calcium deposition in the arterial wall resulting in partial or complete occlusion of the arterial lumen. "The present report suggests a novel relation between diet, AQP5, and atherosclerosis that warrants further investigation and may ultimately open the door to the development of effective new treatments for CVD." (PMID 33557105, 2021).
brain edema (1 paper, 2016). Increased intracellular or extracellular fluid in brain tissue. "Moreover, recent observations have also suggested that the intensity of edema could correlate with specific AQP polymorphisms, as shown in a study on the AQP5 promoter A(-1364)C polymorphism, which is positively correlated with the intensity of brain edema in meningioma patients." (PMID 27367682, 2016).
brain trauma (1 paper, 2024). "The analysis of the literature demonstrated that the most significant markers among the AQPs are AQP4 for the brain, which is very important in brain trauma and hypoxic damage; AQP3 in the skin lesions caused by various mechanisms; and AQP5 in the diagnosis of drowning in lung and kidney samples." (PMID 38473914, 2024). "The analysis of the literature demonstrated that the most significant markers among the AQPs are as follows: for the brain, AQP4, which is very important in brain trauma and hypoxic damage; AQP3 in the skin lesions caused by various mechanisms; and AQP5 in the diagnosis of drowning." (PMID 38473914, 2024).
breast adenocarcinoma (1 paper, 2015). "AQP5 expression in mammary gland/breast adenocarcinoma cell line HTB-22TM, a cell line known to express AQP5, decreased 40% to 80% with exposure to higher concentrations of fluoride compatible to clinical fluorosis in humans." (PMID 26630491, 2015).
Cerebral ischemia (1 paper, 2023). Restriction of arterial blood supply to the brain associated with insufficient oxygenation to support the metabolic requirements of the tissue. "All of these indicate that AE can reduce the expression of aquaporins (AQP3, AQP4, and AQP5) in PSD rats’ brain tissue and alleviate the damage status of depressed rats after cerebral ischemia." (PMID 36982280, 2023).
chromophobe renal cell carcinoma (1 paper, 2022). Chromophobe renal cell carcinoma is a rare subtype of renal cell carcinoma, originating from the intercalating cells of the collecting ducts and macroscopically manifesting as a well-circumscribed, highly lobulated, solid tumor that is usually diagnosed at an early stage. "AQP5 was expressed at lower levels in granular renal cell carcinoma (fold change = −1.803), chromophobe renal cell carcinoma (fold change = −2.080), papillary renal cell carcinoma (fold change = −1.508), and renal oncocytoma (fold change = −1.759) samples than in normal samples." (PMID 36254092, 2022).
chronic lymphocytic leukemia (1 paper, 2023). "Nuclear factor of activated T cells 5 (NFAT5) upregulated Aqp5 mRNA levels in chronic lymphocytic leukemia B cells (MEC-1 cells) and B cells isolated from patients with chronic lymphocytic leukemia, lung adenocarcinoma cells." (PMID 36768212, 2023).
corneal diseases (1 paper, 2024). "Our findings suggest that targeting AQP5 could potentially offer therapeutic opportunities for treating corneal diseases." (PMID 39017635, 2024).
Crohn disease (1 paper, 2024). A gastrointestinal disorder characterized by chronic inflammation involving all layers of the intestinal wall, noncaseating granulomas affecting the intestinal wall and regional lymph nodes, and transmural fibrosis. "A scRNA-seq study of paediatric treatment-naive patients with Crohn’s disease identified MUC6+TFF2+ and BPIFB1+AQP5+ populations, albeit annotated as goblet cells." (PMID 39567783, 2024). "We located INFLAREs (MUC6+AQP5+BPIFB1+) at the crypt base and surface foveolar cells (MUC5AC+) at the crypt top of metaplastic glands in Crohn’s disease mucosa." (PMID 39567783, 2024).
disc degeneration (1 paper, 2015). "Together, our results demonstrate that AQP1 and AQP5 expression is sensitive to human disc degeneration and that HIF-1α uniquely maintains basal expression of both AQPs in NP cells, independent of oxemic tension and HIF-1 binding to promoter HREs." (PMID 25844601, 2015).
ductal carcinoma of breast (1 paper, 2011). "Since tumorigenesis occurs in ductal epithelial cells, and some begin in lobular cells of breast, the observed localization of AQP5 suggests that it may play an important role in tumorigenesis and progression of ductal carcinoma of breast." (PMID 22145049, 2011).
dysplasia (1 paper, 2023). A usually neoplastic transformation of the cell, associated with altered architectural tissue patterns. "AQP5 is positive in SPEM lineage cells at the bases of glands of both pyloric metaplasia and incomplete intestinal metaplasia, but AQP5 is down-regulated in dysplasia." (PMID 37196797, 2023).
endometrial adenocarcinoma (1 paper, 2020). "As 2 reports demonstrated decreased migration of human epithelial ovarian cancer or endometrial adenocarcinoma cells after downregulation of AQP-5, we set out to quantify cell migration of ATII cells differentiated to ATI cells." (PMID 32931478, 2020).
endometrial tumor (1 paper, 2020). "This aspect was observed in a study where overexpression of AQP5 promoted endometrial tumor cell migration, while knockdown of AQP5 decreased migration of these cells." (PMID 33321760, 2020).
fibrosis (1 paper, 2014). the formation of excess fibrous connective tissue in an organ or tissue in a reparative or reactive process. "From these findings we suggest that the early loss of AQP-5 described in different fibrosis models is not necessarily connected with the development of this disease but somehow connected with the function of other proteins of AT I cells." (PMID 24941004, 2014).
fluorosis (1 paper, 2015). "Since these associations suggested that AQP5 may be inhibited by levels of fluoride in the drinking water that cause fluorosis, we showed that fluoride levels above optimal levels change AQP5 expression in humans, cell lines, and rats." (PMID 26630491, 2015). "We evaluated the expression of AQP5 in whole saliva from humans and demonstrated that the expression is lower in individuals from areas where fluorosis can be found." (PMID 26630491, 2015). "AQP5 expression in whole saliva of individuals from areas with fluorosis is decreased (p = 0.04)." (PMID 26630491, 2015).
gastric cardia adenocarcinoma (1 paper, 2025). A carcinoma that arises from glandular epithelial cells of the cardia of stomach. "Results from gastric cardia adenocarcinoma indicate that nicotinamide N-methyltransferase (NNMT) is enriched in AQP5 expressing stem cells and that their stemness is maintained by NNMT-mediated nicotinamide metabolism, which causes reduction of H3K27 trimethylation and activation of WNT signaling." (PMID 40102611, 2025).
gastric cardia carcinoma (1 paper, 2025). A carcinoma that arises from epithelial cells of the cardia of stomach. "For instance, CD24+CD44+EpCAM+ gastric CSCs are significantly associated with poor patient prognosis, and the NNMT+/AQP5+ phenotype could serve as a potential diagnostic marker for gastric cardia cancer." (PMID 40665579, 2025).
gastroenteritis (1 paper, 2022). An inflammatory disorder that affects the upper and lower gastrointestinal tract. "The absence of AQP5 promoted the resistance of mice to gastroenteritis." (PMID 35538066, 2022).
glioblastoma (1 paper, 2017). The most malignant astrocytic tumor (WHO grade IV). "Results showed that the positive expression of AQP5 in primary glioblastoma was associated with the tumor size and whether complete excision was performed." (PMID 28404978, 2017). "The positive expression of AQP5 in primary glioblastoma was associated with the tumor size and whether complete excision was performed (P < 0.05)." (PMID 28404978, 2017). "Compared with the normal brain tissue, the expressions of AQP5 significantly increased in primary glioblastoma, and distributed both in cytoplasm and nuclei." (PMID 28404978, 2017). "These indicated that AQP5 over expressed in primary glioblastoma." (PMID 28404978, 2017).
H. pylori (1 paper, 2022). "It was found that after H. pylori WT infection, AQP5 expression was elevated in primary GECs of mice in a time- and dose-dependent manner." (PMID 35538066, 2022).
Hydrocephalus (1 paper, 2024). Hydrocephalus is an active distension of the ventricular system of the brain resulting from inadequate passage of CSF from its point of production within the cerebral ventricles to its point of absorption into the systemic circulation. "Moreover, the upregulation of AQP5 and downregulation of AQP1 with an apical localization in choroid plexus epithelial cells were observed in hydrocephalus following IVH." (PMID 39839745, 2024).
Hyperkeratosis (1 paper, 2022). Hyperkeratosis is a histopathological term defining a thickened stratum corneum and may be present in many different skin conditions, with many possible overlaps. "The severe clinical findings in affected PPK2 family members could possibly be a combined effect of variants AQP5 (NM_001651.4): c.103T>G (p.(Trp35Gly)) and FLG (NM_002016.2): c.1501C>T (p.(Arg501Ter)), which co-segregate with hyperkeratosis in the family." (PMID 36076978, 2022).
Infertility (1 paper, 2024). "The PDE4 inhibitor rolipram and the different pathways such as IL-6/NF-κB/TNFα/MAPK and cAMP/AQP5 mediating its effects against ovarian torsion damage may be a promising target for ovarian damage or infertility." (PMID 38453769, 2024).
intervertebral disc degeneration (1 paper, 2015). "Objectives of this study were to investigate whether AQP1 and AQP5 expression is altered during intervertebral disc degeneration and if hypoxia and HIF-1 regulate their expression in NP cells." (PMID 25844601, 2015).
lens diseases (1 paper, 2012). "PKA-mediated regulation of AQP5 holds promise for therapeutic intervention to control corneal and lens diseases." (PMID 22550388, 2012). "The study further identified that regulating AQP5 by manipulating phosphorylation could be a tool for therapeutic intervention to control corneal and lens diseases." (PMID 22550388, 2012).
leukemia (1 paper, 2008). A malignant (clonal) hematologic disorder, involving hematopoietic stem cells and characterized by the presence of primitive or atypical myeloid or lymphoid cells in the bone marrow and the blood. "With RT-PCR analysis, K562, EM-2, and LAMA-84 human CML cell lines and U937 human monoblastic leukemia cell line showed a clear expression of AQP5." (PMID 18612408, 2008).
melanoma (1 paper, 2010). A malignant, usually aggressive tumor composed of atypical, neoplastic melanocytes. "The expression of AQP3, as well as AQP1, AQP5, and AQP9 seem to be correlated with melanoma progression, indicating a common pattern of downregulation from the higher values in normal skin and benign nevi." (PMID 20805891, 2010).
Menière's disease (1 paper, 2012). "We speculate, therefore, that AQP5 expression in the apical turns of the cochlea only may play a limited role in inner ear fluid homeostasis in patients with Menière's disease." (PMID 23762616, 2012).
metastatic disease (1 paper, 2022). "Evidence also supports the activation of aquaporin-5 by CagA-positive H. pylori infection, which promotes epithelial–mesenchymal transition via the extracellular signal-regulated kinase/mitogen-activated protein kinase (MEK/ERK) pathway, thus laying the foundation for metastatic disease." (PMID 36230809, 2022). "The evidence supports the activation of aquaporin-5 by CagA-positive H. pylori infection, which promotes epithelial–mesenchymal transition via the extracellular signal-regulated kinase/mitogen-activated protein kinase (MEK/ERK) pathway, thus laying the foundation for metastatic disease." (PMID 36230809, 2022). "Evidence supports the activation of aquaporin-5 by CagA-positive H. pylori infection, promoting epithelial–mesenchymal transition via the extracellular signal-regulated kinase/mitogen-activated protein kinase (MEK/ERK) pathway, thus laying the foundation for metastatic disease." (PMID 36230809, 2022).
mucoepidermoid carcinoma (1 paper, 2020). A carcinoma morphologically characterized the presence of cuboidal mucous cells, goblet-like mucous cells, squamoid cells, cystic changes, and a fibrotic stromal formation. "Mucoepidermoid carcinomas have been shown to exhibit increased expression of AQP5 and among all cell lines analyzed, HMC-3A expressed AQP5 highest." (PMID 33255850, 2020).